CD4 (CD4 molecule)
Diseases named in the same sentence as CD4 in open-access papers (continued):
Sharing a sentence is not in itself a finding about the gene and the disease.
asthma (continued). "IL-17, a proinflammatory cytokine mainly derived from CD4+ T cells and also from monocytes, mast cells, macrophages, and neutrophils, has been suggested in modulating various inflammatory diseases like asthma in humans." (PMID 24995020, 2014). "Some studies have suggested that pulmonary CD4+CD25high Tregs are impaired in pediatric asthma." (PMID 24995020, 2014). "However, further studies linking methylation in varied cell types to asthma outcomes are needed to determine the superiority of CD4+ lymphocytes versus buccal cells as a biomarker for allergic asthma." (PMID 24891923, 2014). "The decreased population of Th3 iTreg cells may, therefore, contribute to the presence of airway inflammation and to asthma progression since there is a correlation between the percentage of CD4+Foxp3+TGF-β+ cells and FEV1." (PMID 25132806, 2014). "To check whether the beneficial effects of Pam3Cys treatment on asthma manifestations could have been mediated by an increased presence of Treg cells, we measured by flow cytometry the numbers of CD4+CD25+Foxp3+ cells in the BAL infiltrates." (PMID 23393567, 2013). "We have shown that the majority of IL-22-producing cells at the site of allergic airway inflammation are CD4+ T cells and that one third of the IL-22-producing CD4+ T cells produce IL-17A, suggesting that some of IL-22-producing CD4+ T cells in a murine asthma model are Th17 cells." (PMID 23577040, 2013). "Since by far the greatest enrichment was observed at enhancers of CD4+ T cells which are known to contribute to asthma, our approach is capable of simultaneously prioritizing those SNPs that are more likely to contribute to a given disease, and identifying the cell types involved." (PMID 23382893, 2013). "Finally, Budesonide with Formoterol reduced IL-17A levels in P and Ss, CD4+IL-17A+T-cells, in naïve children with mild-moderate asthma/persistent rhinitis after 12 weeks of treatment." (PMID 23573194, 2013). "To examine the effect of the GSNOR inhibitor, SPL-334, on allergic airway inflammation and whether the inhibitor limited the inflammation mediated by fully differentiated CD4+ Th2 cells, we used the passive transfer of Th2 cell model of asthma." (PMID 23936192, 2013). "In the context of our previous report that activated AM from an acute exacerbation are able to stimulate Th2 cytokine secretion by primed CD4+ T cells, these results strongly suggest a role for these AM in driving IL-33-dependent inflammation in an acute exacerbation of asthma." (PMID 23936781, 2013). "In isocyanate-induced asthma the importance of CD4+ and CD8+ T-lymphocytes was already shown." (PMID 24349469, 2013). "However, we found that asthma- SNPs enrichment in CD4+ T cell H3K27ac peaks was essentially the same as in CD4+ T cell H3K4me1 peaks." (PMID 23382893, 2013). "Furthermore, the percentage of CD177+IL-17+ neutrophils was elevated in patients with mild asthma, whereas the CD4+ IL-17+ lymphocyte population was higher in asthmatic patients and highest in those with moderate but persistent asthma." (PMID 23822853, 2013). "Additionally, almost all asthma SNPs that belong to CD4+ T cell H3K27ac peaks were also located in CD4+ T cell H3K4me1 peaks (230 out of 254)." (PMID 23382893, 2013). "The key inflammatory cells involved in COPD (CD8+ T cells, macrophages and neutrophils) are different from those involved in asthma (eosinophils and CD4+ Th2 cells), suggesting that different treatments may be required." (PMID 23866260, 2013). "Th2 cytokines, IL-4, IL-5 and IL-13 produced by activated CD4+ T cells, play a central role in the pathogenesis of asthma by controlling the key process of immunoglobulin E (IgE) production, growth of mast cells and the differentiation and activation of mast cells and eosinophils." (PMID 22514638, 2012).
asthma (continued). "Moreover, intrinsic CD4+CD25+ nTreg cells are often defective in suppressing allergic immune responses in asthma patients, which limits the clinical use of these nTreg cells as autograft therapeutic agents." (PMID 22792275, 2012). "Furthermore, children with asthma show quantitative and functional impairment of CD4+CD25+ Treg cells in the BAL fluid, while children that have outgrown their allergy have increased frequencies of allergen-responsive Treg cells." (PMID 22347409, 2012). "However, adoptive transfer experiments show very clearly that sensitized CD4+ T cells from WT spleens were able to reverse the effect of ELP deletion in developing an asthma phenotype although of a smaller magnitude than sensitized and challenged WT." (PMID 21835035, 2011). "In addition, our gene expression analyses include gene transcript measurements from unstimulated peripheral blood CD4+ lymphocytes in a population of adolescents and young adults recruited on the basis of childhood asthma." (PMID 21473777, 2011). "CD4+ NKT cells may also have a critical role in the pathogenesis of asthma and produce IL-5 when co-cultured with CD1d+ antigen presenting cells and IL-2." (PMID 21423619, 2011). "Indeed, in an experimental rat asthma model, adoptively transferred CD4+ T cells from OVA-sensitized rats increases ASM mass, which is both associated with an increased ASM proliferation and decreased apoptosis ex vivo." (PMID 22220184, 2011). "Suppression of cytokine production in activated CD4+ T cells may be useful for the treatment of asthma." (PMID 21772663, 2011). "We examined whether naïve CD4+ T cells or in vivo primed CD4+ T cells isolated from DO11.10x RAG2-/- would be more suitable for this asthma model." (PMID 22014099, 2011). "Unexpectedly, we also showed a weak correlation between IL-10 producing CD4+ T cells and the severity of asthma which may suggest that the expression of this cytokine is associated with aggravated allergic inflammation." (PMID 21197090, 2010). "Next, we examined whether reduced CD4+CD25+ number and CD25+ cell suppressive activity in cord blood were associated with having a maternal history of asthma." (PMID 19586545, 2009). "In addition, IL-25 mRNA is expressed in the lung in an animal model of asthma and neutralization of the produced IL-25 by soluble IL-25 receptor decreases antigen-induced eosinophil and CD4+ T cell recruitment into the airways." (PMID 18315837, 2008). "Finally, in an animal model of asthma CD4+CD25+ T cells isolated from anti-IL-6R antibody-treated mice exhibited marked immunosuppressive and antiinflammatory functions." (PMID 18315837, 2008). "In asthma, blood CD4+ T cells express increased mRNA for interleukin (IL)-4, IL-5, and granulocyte macrophage colony stimulating factor, and IL-5 mRNA expression correlates with asthma severity and eosinophilia." (PMID 16393658, 2006). "Thus, we speculated that miRNAs may regulate CD4+T cell differentiation to participate in the progression of asthma." (PMID 39867638, 2025). "Also, we observed an association with an increased frequency of CD4+ CRTH2+ memory T cells with T2 features independent of asthma status, representing a common T2‐feature‐associated signal." (PMID 40965120, 2025). "It affects multiple immune cells; it reduces the ability of dendritic cells to prime naïve CD4+ cells, it reduces IL-17 production by Th17 cells, it reduces mast cell activity and it suppresses the recruitment of eosinophils and neutrophils to the lung in mouse models of asthma." (PMID 40565065, 2025). "In addition, asthma was enriched in colocalizations derived from CD4+ T-cells (enrichment = 4.34; p = 5.14E − 19) and CD8+ T-cells (enrichment = 3.10; p = 4.91E − 05) meQTLs, which was also replicated by GenoSkyline-Plus (p = 3.43E − 03 and p = 3.92E − 05, respectively)." (PMID 39407252, 2024). "Similarly, it was downregulated in CD4 + T cells from peripheral blood and spleen of asthma mice." (PMID 39342146, 2024).
asthma (continued). "It is reasonable to speculate that PLZF could promote CD4+ TRMs and aggravate asthma." (PMID 39632661, 2024). "However, a recent study found that Th2 and Th17 cells are reciprocally regulated in asthma, thus suggesting that an imbalance in CD4+ T cells may lead to the development of progressive inflammatory and allergic diseases such as asthma." (PMID 38378549, 2024). "Our MR analyses implied that the protective causal effects of asthma on COVID-19 infection/severity were mediated by abnormal change of multiple immune-related cells, mainly including the CD4+ T cells, CD8+ T cells, the ratio of CD4+ T/CD8+ T and the monocyte cells in peripheral blood." (PMID 38263182, 2024). "One more time, the relationship between asthma and thyroidal diseases may be explained by the fact that both share same inflammatory mechanisms, in this case involving a pro-inflammatory subpopulation of CD4+ lymphocytes, Th1 and Th17 pathways." (PMID 37920579, 2023). "In this study, we used ACC1-deficient (Cd4-Cre::Acc1fl/fl) mice and adoptive transfer experiments to determine whether ACC1-mediated fatty-acid metabolism in iNKT cells participates in the development of asthma." (PMID 37917548, 2023). "Although ADNP has not been identified as a common factor in asthma susceptibility, unlike IL-4, IL-5, and IL-13, it was reported among a subset of genes that were differentially expressed by CD4+ lymphocytes and that predicted more atopic from less atopic children." (PMID 37285842, 2023). "Notably, ATG5 participates in the pathogenesis of asthma by mediating the differentiation of CD4+ T cells, which suggests that it may have a potential relationship with Th1 and Th2 cells in asthma patients." (PMID 37644509, 2023). "Therefore, eosinophil-rich type 2 airways may harbour more CD4+TRMs, and it has been shown that CD4+-TRM are associated with asthma severity." (PMID 36851616, 2023). "The aim of this study sought to better understand the prevalence and define the characteristics of CD4+ TEMS in a healthy population that can serve as a comparison cohort for patients with asthma or other respiratory conditions that may be adversely affected by C. pneumoniae infections." (PMID 36301027, 2022). "Thus, a neutrophil/TGF-β axis acts during TLR-mediated allergic sensitization to fine-tune the phenotype of developing allergen-specific CD4+ T cells and limit their pathogenicity, suggesting a novel immunotherapeutic approach to control eosinophilia in asthma." (PMID 35191395, 2022). "In addition to the increase in ILC3s after SLIT, these findings suggest that the improvement of asthma symptoms during the JCP dispersal season after SLIT was associated with an increase in peripheral blood ILC3s and decrease in CD27-negative CD4+ and γδ T cells during the off-season." (PMID 35454107, 2022). "CTCF was also found to be recruited in asthma risk-related SNPs of the ORMDL3 gene and increased the activity of its enhancer in naïve CD4 T cells, which was essential for the repression of Il2 expression in the same cell type, a mechanism that may contribute to asthma progression." (PMID 35812421, 2022). "Thus, smoking in asthma specifically increased the frequencies of CD4+CD45RO+ILC3s in the blood." (PMID 35789151, 2022). "Similar analyses with the asthma patients with normal lung function showed again that although smoking did not significantly alter the blood frequencies of total ILCs or the three ILC subsets, it did associate with significantly higher circulating CD4+CD45RO+ILC3 frequencies." (PMID 35789151, 2022). "In addition, CD4+ T cell reactions in asthma should be considered as irAEs." (PMID 35029177, 2022). "Allergic asthma is the most common asthma phenotype, and Th2 immunity is classically thought to be important in mediating bronchial inflammation during allergic asthma by cytokines such as IL-4, IL-5, and IL-13 produced from CD4 + Th2 cells and innate lymphoid cells." (PMID 34194525, 2021).
asthma (continued). "Furthermore, our study found that the changes of CD4+ T cells and CD8+ T cells in the early life of offsprings may be the potential mechanism for the age-dependent association of CD with asthma." (PMID 34970272, 2021). "Moreover, to better understand the mechanism underlying the food allergy-induced aggravation of asthma and the role of CCR9, they performed adoptive transfer of CD4+ T cells from food-allergic mice into naïve mice, which were subsequently sensitized to house dust mites." (PMID 34490243, 2021). "Thus, GITRL may promote the development of asthma by modulating the differentiation of CD4+ T cells and disturbing the balance of Th1/Th2 and Th17/Treg cells." (PMID 33557842, 2021). "In terms of immune and inflammatory cells expressing ORMDL3, CD4+ cells expressing SNPs linked to ORMDL3 have enhanced Th2 responses, suggesting that ORMDL3-regulated pathways in CD4+ cells may be the key cell implicating ORMDL3 in asthma." (PMID 33661765, 2021). "Thus, it may be that enhanced ORMDL3-dependent modulation of sphingolipid synthesis in CD4+ T cells results in improper allergic or neutrophilic inflammatory responses across the clinical spectrum of asthma phenotypes." (PMID 33424845, 2020). "Although Th2, Th17, and Treg cells, which are CD4+ T cells, are important in asthma pathogenesis, other innate and adaptive immune cells are reported to be involved in the complex inflammatory cascade in asthma, ultimately resulting in the asthma phenotype 6-8." (PMID 32549755, 2020). "Finally, we examined DNAm-asthma associations using a standard EWAS approach, regressing methylation levels for all CpGs on asthma status in unadjusted models and models adjusted for sex, CD4+ T-cells, CD8+ T-cells, monocytes, eosinophils, natural killer, and granulocytes." (PMID 31367216, 2019). "Thanks to this kind of studies, we know now that bronchial neutrophilia in bronchoalveolar lavage fluid is associated with severe asthma independent of oral corticosteroid intake, as well the elevated CD4+ cells expressing both IL-4 and IL-17 predicted greater asthma severity." (PMID 30598830, 2018). "One could thus expect an increase of α4+ CD4+ T cells in asthma patients." (PMID 29507584, 2018). "Thus, future studies on T cell BACH2 might best be directed toward disease where these CD4+ T cell subsets are more important, such as multiple sclerosis or asthma, which are Th17 and Th2 cell-dependent, respectively." (PMID 30459773, 2018). "Moreover, iNKT cells induce asthma even when CD4+ T cells are absent; when MHC II-deficient mice (which lack conventional CD4+ T cells but have iNKT cells) were challenged with α-GalCer, the mice developed AHR equally as well as the wild-type mice." (PMID 30319649, 2018). "However, asthma severity was inversely correlated only with the frequency of CTLA-4+ CD4+ T cells." (PMID 29507584, 2018). "However, the frequency of α4+ CD4+ T cells in patients correlated with asthma severity." (PMID 29507584, 2018). "However, little is known about whether or not C5a-C5aR could be activated by RSV, and there is seldom report about the regulatory mechanisms between C5a-C5aR and CD4+T cells in RSV-induced asthma exacerbation." (PMID 29123203, 2017). "Of note, as C5aRA could reverse some of pathology and CD4+T cells immune changes in RSV-infected asthma mice, C5a-C5aR may represent a potential therapeutic target in the treatment of this condition, and the further underlying mechnisms demand more exploration." (PMID 29123203, 2017). "Multivariable regression found the COPD phenotype associated with greater age and pack-years smoking; the asthma phenotype with younger age, female gender, smoking history, and lower adiponectin levels; and greater WA% with greater BMI, younger age, higher soluble CD163, and higher CD4 counts." (PMID 27488495, 2016).
asthma (continued). "In order to define all the distal cis-regulatory elements that potentially regulate ORMDL3 expression in an asthma-risk genotype-dependent manner, we performed 4C-Seq assays in primary CD4+ T cells from subjects homozygous for the risk (n=4) and non-risk alleles (n=4)." (PMID 27848966, 2016). "We use human/mouse CD4+ T cells to see whether IL-27 could inhibit IL-4 production in vitro and then observe whether IL-27 administration could alleviate allergic airway inflammation in vivo by mice asthma model." (PMID 27687913, 2016). "However, a Th17-biased response has also been observed in patients who exhibit allergic inflammation, particularly in those with severe asthma who respond poorly to steroids, in whom inflammatory cellular infiltration in the airway is primarily due to CD4+ Th17 cells." (PMID 26076663, 2015). "To test the role of PARP-1 in CD4+ T cell function during an allergic response, we examined whether adoptive transfer of WT CD4+ T cells isolated from OT-II mice that were skewed in vitro toward a Th2 phenotype reverses asthma-like traits in naïve PARP-1−/− mice upon OVA exposure." (PMID 26169874, 2015). "Th2- immune responses itself are controlled by regulatory T-cells and it is hypothesized that H. pylori-specific CD4+ T-cells are accumulated in the infected gastric mucosa by H. pylori and could lead to Th2-biased immune responses that initiate the development of asthma and allergic diseases." (PMID 23825730, 2013). "Furthermore, because CD4+ T cells play a central role in asthma pathogenesis, we hypothesized that Gilt−/− animals would display lessened asthmatic symptoms following intranasal challenge with a GILT-dependent allergen." (PMID 23326313, 2013). "In adoptive transfer experiments DCs from asthma-at-risk pups to normal pups, but not macrophages, CD4 T-cells, or DC-depleted splenocytes, caused increased susceptibility to asthma in the recipients, indicating that DCs of asthma-at-risk pups are skewed early in life to induce allergic responses." (PMID 23950928, 2013). "In a murine model of ovalbumin-induced asthma, inhibition of lung inflammatory process, by S. mansoni eggs or by the S. mansoni antigens, Sm22.6, PIII, and rSm29 were associated with an increase in the number of CD4+CD25+Foxp3+ T cells and high levels of IL-10 production." (PMID 23209879, 2012). "Therefore, suppression of Th2 cytokine production in activated CD4+ Th cells may be useful for the treatment of inflammatory immune diseases including asthma." (PMID 22203879, 2012). "The asthma-associated region 17q12-q21 harbors three genes, the zona pellucida binding protein 2 (ZPBP2), gasdermin B (GSDMB) and ORM1-like 3 (ORMDL3), that show allele-specific differences in expression levels in lymphoblastoid cell lines (LCLs) and CD4+ T cells." (PMID 22271045, 2012). "Therefore, suppression of Th2 cytokines production in activated CD4+ Th cells may be useful for the treatment of inflammatory immune diseases including asthma." (PMID 21772663, 2011). "Increased production of IL-4 and IL-13 in both CD4+ and CD8+ T cells accompanied by decreased IFN-γ expression in CD4+ T cells may be evidence that both lymphocyte subpopulations are implicated in the pathogenesis of asthma." (PMID 21197090, 2010). "Although IL-17A is expressed on CD4 cells in the animal model of multiple sclerosis, experimental allergic encephalitis, IL-17A is expressed also on other cells, such as macrophages in asthma, CD8 cells in Behcet disease and psoriasis, and mast cells in rheumatoid arthritis synovium." (PMID 21062492, 2010). "In our study, we could not find any differences regarding IL-10 production by T cells between children with asthma and healthy controls, which is in line with the findings from other studies, but a trend towards higher cytokine level in the CD4+ T in children with severe asthma was observed." (PMID 21197090, 2010).